HMGB1 (high mobility group box 1)
Diseases named in the same sentence as HMGB1 in open-access papers (continued):
Sharing a sentence is not in itself a finding about the gene and the disease.
diabetes (continued). "Given that anti-HMGB1 treatment reversed newly diagnosed diabetes, spontaneous diabetic NOD females were treated with sub-therapeutic doses of insulin for at least 4 weeks prior to transplantation, and by then almost no functional beta cells could be detected." (PMID 32072192, 2020). "Another IR-related gene Hmgb1, is an important mediator during diabetes onset and progression." (PMID 31833538, 2020). "Diabetes led to a 2.2-fold increase on HMGB1 mRNA levels in D0 rats SMG (P = 0.002)." (PMID 32750068, 2020). "We thus sought to explore the therapeutic role of HMGB1 after overt diabetes occurs." (PMID 32072192, 2020). "Moreover, a correlation between HMGB1 levels and diabetes complications has been found in both animal models and in humans with type 2 diabetes." (PMID 33114431, 2020). "RAGEs act as receptors for HMGB1 and, in diabetes, their expression is enhanced." (PMID 32722545, 2020). "As expected, blockade of HMGB1 prevented insulitis progression and decreased diabetes incidence." (PMID 32072192, 2020). "Additionally, we investigated the HMGB1-cleaving properties of DPP-IV as this protease has been reported to cleave HMGB1 with implications for diabetes, and is detected at increased levels in arthritic synovium." (PMID 33391251, 2020). "Retinal HMGB-1 protein expression was significantly higher in the diabetic rats than in the normal ones, and Cs-A treatment significantly reduced this effect induced by diabetes." (PMID 32019593, 2020). "Our results suggest a mechanism of action of LPLI, where it could efficiently down-regulate diabetes-induced HMGB1 and TNF-α expression." (PMID 32750068, 2020). "The actions of HMGB1 in diabetes have been closely investigated since elevated expression levels of HMGB1 have been observed in patients with diabetes and its multiple complications including retinopathy, nephropathy, cardiomyopathy, liver injury, and peripheral neuropathy." (PMID 31165005, 2019). "According to recent researches, plasma HMGB1 levels significantly increased in diabetic patients and HMGB1 was involved in the pathological development of diabetes and related complications by regulating cellular response to oxidative stress and its proinflammatory effect." (PMID 31929852, 2019). "We hypothesized that long-term inhibition of HMGB1 using glycyrrhizin would protect the retina against diabetes-induced damage." (PMID 31269685, 2019). "We have previously shown that diabetes increased HMGB1 levels, which was inhibited by glycyrrhizin." (PMID 31159195, 2019). "Likewise, streptozotocin (STZ)-induced type 1 diabetes mellitus mice exhibit higher myocardial and circulating HMGB1 levels compared with control animals." (PMID 30306212, 2019). "HMGB1 was also recognized to be involved in the development of both type 1 and 2 diabetes." (PMID 30410469, 2018). "For example, HMGB1/RAGE signalling is upregulated in patients with diabetes and atherosclerosis." (PMID 29079726, 2017). "The results from this study suggest that TonEBP haploinsufficiency may have an anti-inflammatory effect in HFD/STZ-induced diabetes by reducing HMGB1-mediated inflammation." (PMID 28798347, 2017). "Notably, the inhibition of HMGB1 release by simvastatin resulted from the inactivation on NLRP3 inflammasome, which was associated with recovery of diabetes-induced vascular permeability." (PMID 29207644, 2017). "Treatment with LPLI reduced the diabetes-induced accumulation of HMGB1, AGE and RAGE expression." (PMID 28099448, 2017). "Third, other clinical characteristics of the study group, such as the rates of hypertension, diabetes or hypercholesterolemia, may have masked the associations between the RAGE and HMGB1 variants and IS." (PMID 29245967, 2017). "In addition, constant glycyrrhizin intake from the onset of diabetes significantly attenuated HMGB-1 expression and activated ERK1/2 in retina." (PMID 27847406, 2016).
diabetes (continued). "As oxidative stress is a central step leading to EPC dysfunction in diabetes and thus contributes to cardiovascular impairment, we hypothesize that diabetes induces the upregulation and release of HMGB-1 in late EPCs via oxidative stress." (PMID 26798412, 2016). "Similarly, HMGB-1 was reported to be upregulated in fibroblasts, macrophages, and cardiomyocytes isolated from diabetes mellitus subjects." (PMID 27847406, 2016). "Increasing evidence indicates HMGB1 is a vital mediator in the onset and progression of diabetes." (PMID 28101517, 2016). "Besides, several other agents such as ethyl pyruvate, quercetin, atorvastatin, and simvastatin were explored in various diseases by targeting HMGB-1; however, their protection effects in diabetes and its complications needed further investigations." (PMID 27847406, 2016). "Taken together, not only is HMGB-1 released in response to hyperglycemia via oxidative stress in diabetes, but also it contributes to the progression of diabetes via inducing islet cells apoptosis and insulin resistance, though the underlying mechanisms are not clearly understood." (PMID 27847406, 2016). "In addition, the present study suggests that PCE prevents diabetes-induced retinal vascular hyperpermeability by attenuating the HMGB1 signaling pathway via the downregulation of the RAGE-mediated activation of NF-κB." (PMID 26950148, 2016). "Blockade of HMGB1 inhibited diabetes development in younger NOD mice." (PMID 28101517, 2016). "Several hypoglycemic drugs have been considered as HMGB-1-targeted drugs in diabetes care." (PMID 27847406, 2016). "We investigated whether diabetes mellitus (DM) increases the severity of cerebral I/R by enhancing elevated HMGB1 expression after cerebral I/R injury." (PMID 27596007, 2016). "Since then, the role of HMGB-1 in diabetes has been confirmed by other studies." (PMID 27847406, 2016). "Oxidative stress was considered as an important player in regulating HMGB-1 in diabetes." (PMID 27847406, 2016). "Nevertheless, our study strongly demonstrates that PCE may be able to prevent diabetes-induced retinal vascular hyperpermeability via its inhibitory effect on the upregulation of HMGB1 by the RAGE-mediated activation of NF-κB." (PMID 26950148, 2016). "Furthermore, a recent study reported that serum HMGB-1 was positively related to HbA1c level and was an independent predictor for coronary artery disease patients with diabetes." (PMID 27847406, 2016). "However, the role of HMGB-1 in diabetes-induced oxidative stress in late EPCs has received little attention." (PMID 26798412, 2016). "Our results are consistent with previous studies which showed that topical application of HMGB1 to skin wounds in mouse models of diabetes enhanced vessel density, accelerated wound healing, and consistently had chemotactic effects on skin fibroblasts and keratinocytes in vitro." (PMID 25385222, 2015). "Plasma levels of HMGB1 were significantly correlated with diabetes in fully adjusted models." (PMID 26317615, 2015). "Therefore, HMGB-1 can rapidly leak out from the cells of ischemic regions of the diabetic retina, thus inducing angiogenesis." (PMID 24498140, 2014). "In addition, we studied the effect of the HMGB1 inhibitor glycyrrhizin on diabetes-induced biochemical changes in the retina." (PMID 24733965, 2014). "Interestingly, constant intake of GA significantly reduced retinal HMGB1 protein and mRNA expression induced by diabetes." (PMID 24733965, 2014). "Furthermore, our data show that intravitreal injection of HMGB1 in normal rats mimics the effect of diabetes." (PMID 24733965, 2014). "Together, these findings suggest that early retinal neuropathy induced by diabetes is, at least in part, attributable to diabetes-induced upregulation of HMGB1 expression and that inhibiting the release of HMGB1 with constant intake of GA results in less diabetes-induced retinal neuropathy." (PMID 24733965, 2014).
diabetes (continued). "In this study, we explored the hypothesis that HMGB1 plays a pathogenetic role in mediating diabetes-induced retinal neuropathy." (PMID 24733965, 2014). "In addition, coimmunoprecipitation studies showed that diabetes increases the interaction between HMGB1 and RAGE in the retina." (PMID 24733965, 2014). "In addition, coimmunoprecipitation studies showed that diabetes increases the interaction between HMGB1 and RAGE." (PMID 23766563, 2013). "Once diabetes has developed, hyperglycemia can induce HMGB1 secretion and HMGB1 may contribute to the nephropathy and the vascular complications of diabetes by fueling inflammation and promoting tissue damage, especially in the kidney." (PMID 23772226, 2013). "The HMGB1 inhibitor GA attenuated diabetes-induced downregulation of BDNF in the retinas of rats." (PMID 23766563, 2013). "We also examined the effect of intravitreal administration of HMGB1 on the retinas of normal rats and whether constant GA intake suppresses diabetes-induced changes in BDNF expression." (PMID 23766563, 2013). "In addition, the HMGB1 inhibitor GA attenuated diabetes-induced upregulation of HMGB1 and downregulation of BDNF in the retinas of rats." (PMID 23766563, 2013). "Administration of soluble RAGE or blocking antibody can induce a protective effect against inflammation and diabetes and this could be due to the interference with HMGB1 pro-inflammatory functions." (PMID 24073286, 2013). "The fact that peak values of MCP-1 levels were measured in co-culture media after 3 weeks of diabetes while HMGB-1 peaked at tissue level after 8 weeks may just reflect a different temporal implication of the two cytokines in the inflammatory process." (PMID 22768138, 2012). "Additionally, an interesting finding of our study was that the positive correlation between serum HMGB1 and the duration of diabetes may indicate that serum HMGB1 plays a significant role in the underlying mechanisms of diabetes-induced renal disease." (PMID 38481996, 2024). "Findings from the present study highlight for the first time the involvement of HMGB1 in the regulation of ferroptosis in the liver of diabetic animals and the potential of HMGB1 inhibition in the context of liver protection from this form of cell death in diabetes." (PMID 36012572, 2022). "Therefore, in the “mild-course” COVID-19 group, HMGB1 levels could rather be a marker of diabetes mellitus than COVID-19 disease severity." (PMID 36251689, 2022). "Prompted by the observations that an increased HMGB1 in the myocardium occurred prior to macrophage activation, we speculated that HMGB1 actively secreted from stressed cardiomyocytes is crucial in shaping macrophage phenotype in diabetes." (PMID 35281739, 2022). "Finally, we ascertained functional evidence whether targeting HMGB1 has beneficial effects on diabetes-related cardiac dysfunction through anti-inflammatory activity." (PMID 35281739, 2022). "Therefore, taken together with the previous findings, it can be concluded that HMGB‐1 may contribute to diabetes‐induced vascular calcification." (PMID 33724642, 2021). "Thus, we assessed the presence of a positive association between HMGB‐1 and ERS in diabetes." (PMID 33724642, 2021). "Therefore, in the present study, we attempted to indicate whether HMGB‐1 could promote vascular calcification via ERS in diabetes." (PMID 33724642, 2021). "In addition, HMGB1 release and elevated RAGE expression plays a significant role in the pathogenesis of hypertension, hyperlipidemia, and diabetes mellitus, which are the most common risk factors for atherosclerosis and contribute to cerebral vessel occlusion during ischemic stroke." (PMID 33384585, 2020). "In 2012, a hypothesis was reported that secreted HMGB1 acting through RAGE, on monocytes, macrophages, and vascular endothelial cells, and might play an important role in the development of diabetes-associated periodontitis, and many reports regarding this relationship are currently being conducted." (PMID 32760399, 2020).
diabetes (continued). "Thus, in the context of diabetes, HMGB1 may potentially mediate inflammation by activating any or all of TLR2, 4 or RAGE in DN." (PMID 29844451, 2018). "Thus, HMGB-1 may play an important role in diabetes-induced oxidative stress in EPCs via a positive feedback loop involving the AGE/reactive oxygen species/HMGB-1 pathway." (PMID 26798412, 2016). "Thus, we hypothesized that diabetes induces the release of HMGB-1, which subsequently enhances oxidative stress in late EPCs." (PMID 26798412, 2016). "First, this cross-sectional study could not conclude the causality between plasma CTRP-3/HMGB-1 and pre-DM or diabetes; thus a prospective study is required in future research." (PMID 27738641, 2016). "However, HMGB-1 pro-inflammatory toxicity can mediate damage of previously existing and new forming blood vessels as well as can promote infiltration of leukocytes, thereby increasing blood-retinal permeability in the diabetic retina." (PMID 24498140, 2014). "Inhibition of HMGB1 could attenuate diabetes-induced myocardial fibrosis and dysfunction." (PMID 25210949, 2014). "HMGB1 is a typical DAMP that engages TLR4 to activate NF‐κB and prime the NLRP3 inflammasome, thereby amplifying IL‐1β–driven inflammation; diabetes‐related AGEs and ROS further potentiate NLRP3 activation and pyroptosis, delaying epithelial repair." (PMID 41503166, 2026). "Diabetes significantly increased the retinal expression of phospho-ERK1/2, HMGB1, VCAM-1, and ICAM-1 in comparison with the retinal levels in nondiabetic control rats." (PMID 39851513, 2025). "Notably, in type 2 diabetes mellitus models, palmatine shows better restorative effects on insulin signaling pathways compared to metformin and glimepiride, and reduces serum high mobility group box 1 (HMGB1) levels to promote healing of diabetic corneal ulcers." (PMID 40786032, 2025). "The intravitreal administration of ADAMTS13 attenuates diabetes-induced BRB breakdown, the downregulation of VE-cadherin and β-catenin, and the upregulation of VWF, CD41, phospho-ERK1/2, HMGB1, VCAM-1, and ICAM-1." (PMID 39851513, 2025). "Some patients with gastric cancer and diabetes mellitus were found to have elevated expression of receptors for advanced glycation end products (RAGE) and high mobility group protein B1 (HMGB1)." (PMID 40579921, 2025). "Serum HMGB1 and UTP also showed a J-shaped relationship, after excluding the confounding factors of age, sex, hypertension, smokers, and duration of diabetes." (PMID 38481996, 2024). "Age, male proportion, duration of diabetes, hypertension proportion, CVD proportion, smokers’ proportion, and serum TNFR-1 levels increased with increasing serum HMGB1 levels (all p values < 0.05)." (PMID 38481996, 2024). "It blocks HMGB1/RAGE signaling and reduces inflammation as reported in studies employing diabetes-induced atherosclerosis." (PMID 39682695, 2024). "High mobility group box 1 (HMGB1), a DAMP known to be elevated in diabetes, is released upon corneal injury and also acts via TLR4 to initiate inflammation." (PMID 36982926, 2023). "High mobility group box-1 (HMGB1) is a ubiquitous nuclear protein that maintains DNA structure in various cell types and can be released in response to hyperglycemia in diabetes." (PMID 36186139, 2022). "There are numerous DAMPs but some are particularly relevant to diabetes such as monosodium urate (MSU), high-mobility group box 1 (HMGB1), C6-ceramide and AGEs." (PMID 36505062, 2022). "More importantly, consistent observations of increased HMGB1 were made in the myocardium from human diabetic subjects with CVD and serum from patients with diabetes." (PMID 35281739, 2022). "As both HMGB‐1 and ERS played pivotal roles in diabetes‐induced calcification, we further tested the role of ERS in HMGB‐1‐induced calcification in VSMCs." (PMID 33724642, 2021).
diabetes (continued). "In summary, the results of the present study indicated that diabetes induced HMGB‐1 secretion via ERS; in turn, HMGB‐1 induced vascular calcification via excessive activation of ERS." (PMID 33724642, 2021). "Serum HMGB‐1 level and HMGB‐1 expression in aortas were diminished in animal models of diabetes when treated with 4‐PBA." (PMID 33724642, 2021). "Thus, it can be concluded that diabetes may promote expression and secretion of HMGB‐1 via ERS." (PMID 33724642, 2021). "The next aim of the investigation was to ascertain the roles of HMGB‐1 and ERS in diabetes‐induced vascular calcification in diabetic mice." (PMID 33724642, 2021). "In summary, HMGB1, and RAGE are involved in the two-way relationship between diabetes and periodontitis, and metformin has the potential to resolve them." (PMID 32760399, 2020). "There is a functional link between HMGB1 and SIRT1 in the regulation of the diabetes-induced breakdown of the BRB." (PMID 32722545, 2020). "Thus, it is speculated that the effect of HMGB1 on CAM phenotype switching through AC inhibition contributes to the pathogenesis of vasculopathy associated with metabolic disorders such as obesity and diabetes." (PMID 32211403, 2020). "Considering the relationship among HMGB1-RAGE, diabetes, and oxidative stress, we focused on the role of ROS." (PMID 31929852, 2019). "The HMGB1/RAGE axis has been suggested to contribute to the pathogenesis of many diseases such as autoimmune diseases, cancer, and diabetes." (PMID 31165005, 2019). "Blood glucose, incidence of diabetes, body weight, pancreatic histopathology, the amounts of CD4+T cell subsets, IL-1β level in serum and pancreatic expressions levels of HMGB1, and NF-κB p65 protein were analyzed." (PMID 30410469, 2018). "We also found that TonEBP+/− mice had reduced levels of hepatic lipogenic factors, HMGB1, IL-6, and TNF-α expression, as well as reduced macrophage infiltration and proinflammatory cytokines in adipose tissues of HFD/STZ-induced diabetes." (PMID 28798347, 2017). "Diabetes induces inflammation by increasing the expression of RAGE and two endogenous RAGE ligands, HMGB1 and AGE, which activates the downstream NF-κB pathway in SMGs in this rat experimental model." (PMID 28099448, 2017). "High mobility group box1 (HMGB1) promotes inflammatory injury, and accumulating evidence suggests that it plays a key role in brain ischemia reperfusion (I/R), as well as the development of diabetes mellitus (DM)." (PMID 27596007, 2016). "The HMGB1/RAGE axis has been suggested to contribute to the pathogenesis of many diseases such as acute lung injury, preeclampsia, diabetes, cancer, and autoimmune diseases." (PMID 28101517, 2016). "In diabetes-prone NOD mice, HMGB1 blockade significantly inhibited insulitis progression and delayed diabetes onset, decreased the number, and maturation of DCs in the pancreatic lymph nodes, and increased the number of regulatory T cells." (PMID 23772226, 2013). "In the present study, we investigated the correlations between the levels of BDNF and the levels of HMGB1 in the vitreous fluid and serum from patients with PDR and in the retinas of rats with diabetes." (PMID 23766563, 2013). "Evidence suggests that HMGB1 participates in the pathogenesis of many autoimmune diseases like Rheumatoid Arthritis (RA), SLE, EAE, and diabetes." (PMID 23772226, 2013). "In conclusion, these data suggest that diabetes-induced increased oxidative stress, downregulation of BDNF and synaptophysin, and upregulation of cleaved caspase-3 were also induced by HMGB1." (PMID 23766563, 2013). "Diabetes did not alter the expression of HMGB1 and HSP70 in the adrenal glands of Swiss-Webster mice; however, it increased the expression of TLR4 and TRIF compared to non-diabetic mice." (PMID 40496562, 2025).